IL33 (interleukin 33)
Diseases named in the same sentence as IL33 in open-access papers (continued):
Sharing a sentence is not in itself a finding about the gene and the disease.
glioma (continued). "In this study, we illustrate that glioma-derived IL-33 has a dramatic effect on glioma growth in vivo through its ability to alter the cellular state of the tumor microenvironment." (PMID 33020472, 2020). "Initial characterization of the in vivo glioma secretome identified IL-33 as a major constituent of the inflammatory phenotype." (PMID 33020472, 2020). "Using double-label immunofluorescence, we observed that TNC was enhanced in IL-33+ or ST2+ glioma cells." (PMID 31889095, 2019). "In future studies, we will seek to investigate the cellular source of IL-33 in gliomas and examine the relationship among glioma stem cells, IL-33, and TNC." (PMID 31889095, 2019). "A recent study suggested that IL-33 is a key factor in rat glioma cells, and upregulation of IL-33 expression increased tumourigenic activity." (PMID 31889095, 2019). "We have previously indicated that IL-33 overexpression in glioma clinical specimens predicts poor prognosis in patients." (PMID 31889095, 2019). "Our previous work shows that the expression of IL-33 is increased in human glioma at the mRNA and protein levels, and IL-33/ST2 signalling facilitates cancer progression." (PMID 31889095, 2019). "Animal studies demonstrated that IL-33 significantly promoted glioma progression, and immunohistochemical staining showed that treatment with IL-33 significantly increased TNC expression." (PMID 31889095, 2019). "Our previous work and that of others shows that IL-33 is aberrantly expressed in gliomas and promotes tumour progression." (PMID 31889095, 2019). "In the present study, we show that the IL-33/ST2 signalling axis can directly cause TNC expression through the activation of its downstream signalling pathways, mainly NF-κB, to promote glioma progression." (PMID 31889095, 2019). "Here, we showed that downregulation of TNC strongly repressed IL-33-mediated glioma cell invasion but had little impact on migration." (PMID 31889095, 2019). "In this study, our key finding was that IL-33 increased TNC expression and promoted glioma invasion through the IL-33/ST2/TNC signalling axis with activation of NF-κB signalling." (PMID 31889095, 2019). "In conclusion, we have validated that IL-33 can result in the expression of TNC through autocrine or paracrine modes of action in glioma cells via activation of some downstream signalling pathways and can then promote tumour progression." (PMID 31889095, 2019). "To investigate the relationship between IL-33 and TNC, we stimulated glioma cells with different concentrations of IL-33 for 6 h and then examined the expression levels of TNC by RT-PCR and Western blot analyses." (PMID 31889095, 2019). "In all glioma tissues, intense nuclear staining of IL-33 with diffuse staining in the cytoplasm was observed." (PMID 31889095, 2019). "Lu and collaborators detected “significantly higher IL-33 expression in glioma tissues than in normal brain tissues through immune-histochemical (IHC) analysis”." (PMID 30416507, 2018). "Further evidence indicates that the involvement of IL-33 in glioma cell invasion and migration is through upregulation of MMP2 and MMP9 via the ST2-NF-κB signaling pathway." (PMID 30515150, 2018). "Even in the brain, IL-33 in the TME induces growth of glioma cells and facilitates microglia/macrophage infiltration." (PMID 30416507, 2018). "In all, IL-33 mediated the development of a microenvironment that facilitated microglia/macrophage infiltration to promote glioma growth in the brain." (PMID 30205617, 2018). "It has become clear that the IL-33/ST2 signaling pathway facilitates glioma cell proliferation and migration, as treatment of the cells with IL-33 shRNA or ST2 shRNA reduces cell growth and colony formation in culture and reduces tumor volume in vivo." (PMID 30515150, 2018). "Analysis of human glioma tissue arrays by immunohistochemistry showed that IL-33 was expressed heterogeneously in tumor tissue but was undetectable in normal brain tissue." (PMID 30205617, 2018).
glioma (continued). "High IL-33 expression in glioma was correlated with shorter overall survival (OS) and progression-free survival (PFS)." (PMID 30416507, 2018). "All of these data suggest a pivotal role for IL-33 in the disease pathogenesis and as a potential biomarker for prognosis of human gliomas." (PMID 30515150, 2018). "Blockade of IL-33 or ST2 attenuated cell growth and colony formation as well as cell migration and expression of glioma-associated growth factors and chemokines." (PMID 30205617, 2018). "Notably, IL-33 plays a significant role in the activation and recruitment of microglia, highlighting the bidirectional communication between glioma cells and Iba1+ microglia/macrophages." (PMID 40136662, 2025). "In summary, our study demonstrates that the absence of the IL-33 receptor ST2 is associated with increased tumor invasion, vascular abnormalization, and immunosuppression in murine glioma models where IL-33 is predominantly expressed by oligodendrocytes in the tumor environment." (PMID 39931535, 2025). "Additionally, IL-33 was reported to promote the maturation and antigen-presenting capacity of DCs,54,55 facilitating the activation of T-cell responses against glioma antigens." (PMID 39931535, 2025). "Investigations by Zhang and his colleagues in 2019 suggest that TN-C expression in glioma tissue may be promoted by the interleukin-33 (IL-33)-ST2-nuclear factor kappa B (NFκB) pathway." (PMID 38732975, 2024). "However, IL-33 pro-tumor function has been noted in multiple cancers, including glioma, gastric, and colorectal cancers." (PMID 38816352, 2024). "Human interleukin-33 (IL-33), belonging to the IL-1 family, is a cytokine that mediates endogenous cellular alerts and exerts a tumor-promoting effect in various types of tumors, gliomas included." (PMID 37700840, 2023). "More recently, a study indicated that IL-33 accelerates the invasion of glioma cells." (PMID 35927251, 2022). "Furthermore, glioma cells rich in IL-33 have high CCL7 expression levels and thus promote microglial infiltration." (PMID 36439205, 2022). "Thus, microglial activation state transitions induced by IL-33 provide a protective function in neuroinflammation except in gliomas, where M2 microglia are considered tumor-forming promoting immune cells." (PMID 36439205, 2022). "Interestingly, IL33 expression in DIPG patients is significantly higher than in patients with cortical low-grade glioma or medulloblastoma." (PMID 35990702, 2022). "It is now clear that IL-33 plays a pro-tumorigenic role in various cancers including glioma." (PMID 36555253, 2022). "Thus, before initiating treatment, high levels of IL-6, IL-8, IL-17, IL-33, TNF-α, TGF-β, and CRP in the circulation are strongly associated with increased glioma stem cell activity that potentially leads to glioma progression and greater invasiveness." (PMID 35054779, 2022). "Accumulating evidence suggests a role for IL33 in adult glioma." (PMID 35990702, 2022). "Activation of the JNK pathway was observed also in glioma, where IL-33 and its receptor IL-1RL1 were found overexpressed and were associated with increased cell migration, invasion, epithelial-mesenchymal transition, stemness features and poor patient survival." (PMID 34583655, 2021). "Interestingly, IL-33 is also believed to be involved in the onset of schizophrenia, traumatic encephalopathy, and glioma." (PMID 33854693, 2021). "IL-33 is highly expressed in tumor cells during glioma development." (PMID 34079543, 2021). "In addition, an experiment illustrated that interleukin-33 (IL-33) positively regulated TNC expression in glioma cells, and the IL-33/ST2 axis enhanced glioma cell invasion via assembly of TNC." (PMID 33876384, 2021). "Furthermore, IL-33 was involved in the process of glioma cell invasion and migration by upregulating MMP2 and MMP9." (PMID 32003751, 2020).
glioma (continued). "Collectively, this IL-33-driven tumor environment promotes both the activation of resident microglia and the recruitment of bone-marrow-derived cells that collectively enhance glioma growth and progression." (PMID 33020472, 2020). "The biological role of IL-33 in glioma is poorly understood." (PMID 32003751, 2020). "We found that IL-33 induced sphere formation of both glioma cell lines." (PMID 32003751, 2020). "Consistent with this, using both human and murine glioma models, we found that enforced expression of IL-33 results in the conversion of relatively immune inert glioma to a glioma with an immune rich environment that mediates rapid tumor growth and dramatic decrease in overall survival." (PMID 33447733, 2020). "Representative tumor images demonstrated that IL-33 significantly induced glioma development." (PMID 32003751, 2020). "However, we genetically knocked down IL-33 with specific siRNA and found that si-IL-33 reduced the proliferation of glioma cells." (PMID 32003751, 2020). "Treated with neutralizing mAb against ST2 blocked the effects of IL-33 in glioma cells invasion." (PMID 32003751, 2020). "That meant IL-33 had a certain role in promoting glioma proliferation in vivo." (PMID 32003751, 2020). "The biological role of IL-33 in glioma need to be investigated more deeply." (PMID 32003751, 2020). "Our in vivo experiments proved that IL-33 significantly induced glioma development in nude mice." (PMID 32003751, 2020). "Furthermore, we found that IL-33 promoted epithelial to mesenchymal transition in glioma by detecting the expression of core epithelial and mesenchymal biomarkers." (PMID 32003751, 2020). "We suspected that the glioma cells themselves might express and release large amounts of IL-33, which made the stimulation of exogenous IL-33 insignificant." (PMID 32003751, 2020). "Therefore, we examined the effect of IL-33 on these signaling pathways in glioma cells at different time points." (PMID 32003751, 2020). "In addition, and as observed in vitro, IL-33 was predominantly localized within the nucleus of the glioma cells, while IL-33 was undetectable in the nucleus of the ΔNLS glioma cells in vivo." (PMID 33020472, 2020). "Similarly, the second cohort of mice, bearing control (pcDNA) or ΔNLS IL-33 glioma cells, were monitored until the control mice became symptomatic, ~6 weeks postinjection, at which point all remaining mice were sacrificed and prepared for IHC." (PMID 33020472, 2020). "Moreover, we find that the expression of IL-33 by glioma cells is sufficient to drive tumor progression and reduce overall survival, a function that requires both its secreted and nuclear functions." (PMID 33020472, 2020). "Recently, we found that IL-33 is expressed in a large number of human glioma patient specimens where its expression within the tumor correlates with the increased presence of Iba+ cells that include both resident microglia and recruited monocyte and macrophages." (PMID 33447733, 2020). "While human glioma can have necrotic regions where IL-33 could be released, many in vivo models utilized in this study show very little evidence for necrosis." (PMID 33020472, 2020). "In addition, treatment with recombinant IL-33 (rIL-33) or CM from glioma cells expressing IL-33 or ΔNLS IL-33 were capable of recruiting BMDM in vitro." (PMID 33020472, 2020). "In this context, IL-33 is both secreted by the glioma cells and present within its nucleus." (PMID 33447733, 2020). "Because of IL-33 in promoting EMT and stemness in glioma, the resistant to TMZ caused by IL-33 might be mediated by these biological changes." (PMID 32003751, 2020). "However, there are still a number of unanswered questions, i.e. how is IL-33 secreted from the glioma cells?" (PMID 33447733, 2020). "Our data suggest that interleukin-33 (IL-33) may promote the accumulation of TNC protein by autocrine or paracrine modes of action in glioma." (PMID 31889095, 2019).
glioma (continued). "To ascertain whether TNC is essential for IL-33-induced glioma invasion and migration, we knocked down TNC in U251 cells using shRNA constructs." (PMID 31889095, 2019). "Taken together, this evidence inspires us to investigate the influence of the IL-33/ST2 signalling pathway on TNC expression in glioma cells and to explore whether this signalling pathway promotes tumour progression." (PMID 31889095, 2019). "Herein, we evaluated the role of the IL-33/ST2 axis on the biological behaviour of glioma cells." (PMID 31889095, 2019). "Furthermore, we knocked down IL-33 in U251 glioma cells using shRNA constructs, one of which (shIL-33 #3) caused effective IL-33 silencing." (PMID 31889095, 2019). "IL-33 promoted glioma cell invasion by stimulating the secretion of TNC." (PMID 31889095, 2019). "More importantly, we pretreated glioma cells with IL-33 (50 ng/ml) before transfecting siRNA." (PMID 31889095, 2019). "Interestingly, diminished PRDM1 expression is linked to poor survival and aggravated pathological grade of human glioma and IL-33 is found to express heterogeneously in cancerous tissues and shares an association with inferior survival in patients suffered from relapse GBM." (PMID 35927251, 2022). "Moreover, higher IL-33 expression is associated with poor overall survival (OS) and recurrence-free survival (RFS) in patients with gliomas, indicating that IL-33 might be an independent prognostic marker for glioma." (PMID 34079543, 2021). "Nevertheless, IL-33 might be a promising therapeutic target for glioma." (PMID 34079543, 2021). "Therefore, IL-33 promotes glioma cells migration, invasion, EMT and stemness via JNK activation." (PMID 32003751, 2020). "Thus, ST2 is expressed by glioma cells and mediates IL-33 downstream signaling." (PMID 32003751, 2020). "Thus, understanding the role of IL-33 in tumor regulation may provide valuable information for controlling the malignant behavior of glioma." (PMID 32003751, 2020). "Thus, IL-33 promotes glioma cell migration, invasion and epithelial to mesenchymal transition." (PMID 32003751, 2020). "Furthermore, anti-ST2 blocked the effects of IL-33 in glioma sphere formation." (PMID 32003751, 2020). "Administration of human recombinant interleukin-33 could activate the JNK signal pathway in glioma." (PMID 32003751, 2020). "We believe that IL-33/ST2 axis may be served as a therapeutic target in the treatment of glioma." (PMID 32003751, 2020). "Our study has highlighted a central role for glioma-derived IL-33 as an orchestrator of the brain tumor microenvironment that promotes glioma progression and builds from previous studies, providing more mechanistic insight into the functions of IL-33 in glioma biology." (PMID 33020472, 2020). "Thus IL-33/ST2 axis may be served as a therapeutic target in combination with TMZ chemotherapy in glioma treatment." (PMID 32003751, 2020). "Thus, if one could recapitulate the tumor microenvironment when the nuclear localization of IL-33 is crippled, it may provide an alternative or additional therapeutic strategy for treating glioma patients." (PMID 33447733, 2020). "Therefore, we believe that IL-33 enhances glioma cell invasion by accumulating TNC." (PMID 31889095, 2019). "Thus, targeting the IL-33/NF-κB/TNC signalling pathway may be a useful therapeutic approach in glioma." (PMID 31889095, 2019). "Thus, IL-33 may become a useful biomarker in predicting prognosis in glioma patients, and a novel therapeutic target for glioma treatment." (PMID 30515150, 2018). "Our findings reveal that glia-derived IL-33 and its receptor ST2 participate in modulating tumor invasiveness, tumor vasculature, and immunosuppression in glioma." (PMID 39931535, 2025). "Glioma cell proliferation, including glioma stem cells, results in the secretion of cytokines and chemokines such as MIC-1, periostin, IL-33, and MCP-1, which recruit blood-borne monocytes and macrophages to the tumor site, polarizing them into M2 TAMs." (PMID 37234776, 2023).
glioma (continued). "It has been reported that IL-33 and ST2 expression in glioma tissues is higher than that in normal brain tissues, and their expression is positively correlated with glioma grade." (PMID 34079543, 2021). "However, whether IL-33 competes with TCApF for ST2 binding in glioma is unclear." (PMID 34079543, 2021). "To evaluate the clinical relevance of IL-33 and ST2, we analyzed the survival curves of glioma samples from TCGA database." (PMID 32003751, 2020). "We first examined the expression of IL-33 and ST2 in glioma patients of our hospital by immunohistochemistry (IHC)." (PMID 32003751, 2020). "Thus, targeting the IL-33/ST2 axis may offer an opportunity to the treatment of glioma patients." (PMID 32003751, 2020). "To examine the role of IL-33 in glioma tumorigenesis, EMT and stemness in vivo, we used glioma cell line Ln229 that subcutaneously injected into nude mice with or without IL-33." (PMID 32003751, 2020). "In contrast with control treatment, IL-33 treatment increased TNC expression, and knockdown of IL-33 attenuated TNC expression in glioma cells." (PMID 31889095, 2019). "In the present study, the expression levels of TNC, IL-33, and ST2 were measured in glioma tissue specimens, and the impact of altered IL-33 expression on TNC was investigated in vitro and in vivo." (PMID 31889095, 2019). "We and others have previously shown that in neurodevelopment and neuroinflammation, astrocytes and oligodendrocytes, but not neurons or microglia, express IL-33.21,22,35,36 To investigate if this is the case also in glioma, 2 syngeneic mouse models were used." (PMID 39931535, 2025). "Similar to IL-33 and its downstream mediator IL-6, CD276 may have a role in the activation of STAT3 downstream signaling, which enhances stem-like characteristics in glioma cells and induces an anti-inflammatory phenotype in TAMs." (PMID 40136662, 2025). "Knockdown of IL-33 or ST2 in glioma cell lines suppresses proliferation, migration and invasion in vitro and reduces tumor formation in vivo in both rodent models of intracerebral glioma cell implantation and subcutaneous xenograft." (PMID 34079543, 2021). "However, both IL-33 knockdown and Anti-ST2 antibody significantly reduced the proliferation of glioma cells." (PMID 32003751, 2020). "We found that the mere expression of IL-33 in non-expressing glioma cells is sufficient to promote rapid tumor growth and dramatically reduces the overall survival." (PMID 33020472, 2020). "Glioma cells were cultured with or without IL-33 and were subsequently exposed to TMZ in different concentrations." (PMID 32003751, 2020). "Our work suggests that targeting IL-33 and ST2 signaling may be potentially applicable in targeting EMT and stemness treatment and enhancing the sensitiveness of chemotherapies, for glioma treatment." (PMID 32003751, 2020). "We found that IL-33 and ST2 expression was significantly increased in glioma cells and tissues." (PMID 32003751, 2020). "We hypothesized that IL-33 may induce the TMZ chemoresistance as its role in promoting EMT and stemness in glioma." (PMID 32003751, 2020). "To assess the role of IL-33 in tumor invasion and metastasis, we used two glioma cell lines U251 and Ln229 incubated with or without IL-33." (PMID 32003751, 2020). "Neither of these mouse glioma cell lines express detectable levels of IL-33 when cultured in vitro." (PMID 39931535, 2025). "This is in striking contrast to the presence of both secreted and nuclear IL-33 where expression drives gliomagenesis, an observation independent of whether the data is evaluated from human gene expression analysis, BTIC/glioma cell xenografts, or the PDGFΒ-driven murine glioma mouse model." (PMID 33020472, 2020).